LSP1P5 (LSP1 pseudogene 5 )
Synonyms: LSP1P4
Gene: Long non-coding RNA gene on chromosome 2 (91,586,931 to 91,660,038, reverse strand). Ensembl gene ENSG00000291150.
Diseases named in the same sentence as LSP1P5 in open-access papers:
LSP1P5 is named in the same sentence as 1 disease in open-access papers, as found by Europe PMC text mining. Sharing a sentence is not in itself a finding about the gene and the disease. The quoted sentences say what the papers report.
keloid (1 paper, 2025). An irregularly shaped, elevated mark on the skin caused by deposits of excessive amounts of collagen during wound healing. "lnc-LSP1P5, a known lncRNA, resulted more elevated in the nuclei of fibroblasts in keloids, and it seems to silence CEBPA, which is an antifibrotic factor." (PMID 41007836, 2025).